FOXP3 (forkhead box P3)
Diseases named in the same sentence as FOXP3 in open-access papers (continued):
Sharing a sentence is not in itself a finding about the gene and the disease.
colitis (continued). "From a functional perspective, the adoptive transfer of these cells into a RagKO murine colitis model found that the Treg cells lost FOXP3 expression after 8 weeks, there was an accumulation of IFNγ-producing Th1 cells and thus, the development of colitis was not prevented." (PMID 33013855, 2020). "Importantly, this protective effect was limited to Vβ5+ Treg cells as Vβ8+Foxp3+ Treg cells were not capable of rescuing ΔVβ5 mice from colitis (“ΔVβ5 + Vβ8+ Treg AT”)." (PMID 32251280, 2020). "Mice without RORγt/FoxP3+ T reg cells developed severe inducible experimental colitis." (PMID 31417552, 2019). "Additionally, HO-1 is induced to downregulate retinoic acid-related orphan receptor γt expression and IL-17A levels, while promoting the expression of Treg-related forkhead box p3 (Foxp3) and IL-10 level in dextran sulfate sodium (DSS)-induced acute murine colitis." (PMID 31396090, 2019). "FoxP3+ Tregs were present in a significantly higher numbers in PPs and MLNs of mice from S.obvelata immunized group that received the egg as a prophylactic and therapeutic helminthic therapy against DSS- induced colitis compare to uninfected control and DSS exposed animals." (PMID 31836772, 2019). "In light of these findings, we further demonstrated that combined IL-2/JES6-1 immunocomplex and anti-IL-5 mAb treatment was most effective at ameliorating DSS-induced colitis compared to either treatment alone and that this regimen allowed for Foxp3+ Treg expansion without concomitant eosinophilia." (PMID 30930900, 2019). "Strikingly, FOXP3+ specific conditional knock out mice for MAF did not develop colitis and demonstrated normal levels of IL-10 in their colon, despite the incapacity of regulatory T cells lacking MAF to suppress colon inflammation in Rag1−/− mice transferred with naïve CD4+ T cells." (PMID 30992496, 2019). "In light of these findings, we observed that combined IL-2/JES6-1 and anti-IL-5 mAb treatment was most effective at ameliorating DSS-induced colitis compared to either treatment alone and that this regimen allowed for Foxp3+ Treg expansion without concomitant eosinophilia." (PMID 30930900, 2019). "In support of this interpretation, a previous study demonstrated that mice selectively lacking the Foxp3+RORγt+ Treg subset develop elevated intestinal IL-17A responses at steady state and experience exacerbated immunopathology in a chemically-induced colitis model." (PMID 31889073, 2019). "After a preliminary validation of the ability of anti-LAP antibody administration to selectively deplete LP CD4+LAP+cell without affecting the % of LP CD4+Foxp3+ cells, we administered the antibody or its isotype control in two groups of mice, before the induction of oxazolone colitis." (PMID 30425718, 2018). "Although the underlying mechanisms of B10 Breg and Foxp3+ Treg increase in the spleen and MLN are currently unclear in these experiments in the DSS colitis model, previous studies have outlined two non-mutually exclusive pathways concerning DC-stimulated increases in Treg numbers." (PMID 29774025, 2018). "Whether or not the reduced IL-10 production by Bcl-3-overexpressing Tregs is the sole reason for the colitis is not clear, as we also noticed decreased expression levels of Foxp3, CTLA-4, GITR and IL-2R in these Treg cells." (PMID 28452361, 2017). "Similarly, mice lacking FoxP3+ Tregs or lacking the ability to suppress via Treg-derived cytokines such as IL-10, IL-35, and TGFβ develop severe colitis." (PMID 25944983, 2015). "We previously reported that TAK1 deficiency in T cells resulted in an impaired generation of regulatory T cells and in fact we confirmed a dramatic reduction in the frequency of CD25+Foxp3+ cells in CD4 single positive thymocytes of 6-week-old LTAC mice in which colitis does not appear." (PMID 26132627, 2015).
colitis (continued). "Taken together, these results indicate that MHCII expression by IECs attenuates bacterial-driven colitis by preventing exacerbated effector Th1 cell accumulation and the establishment of an unfavourably altered ratio between conventional CD4+ T cells and FoxP3+ Treg cells." (PMID 24489792, 2014). "In summary, our studies suggest that during colitis, activation of AhR by TCDD may promote anti-inflammatory activity primarily through epigenetic regulation of Foxp3 and IL-17 gene promoters leading to preferential differentiation of Tregs and inhibition of Th17 cells." (PMID 21858153, 2011). "Moreover, TCDD elevated Foxp3 expression in the MLN and LP of mice with colitis." (PMID 21858153, 2011). "Finally, due to the ability of cis-UCA to increase IL-10 secretion, coupled with our observation of a trend towards a cis-UCA-induced increase in FoxP3+IL-10+ T cells in the DSS studies, we next carried out a series of experiments in the IL-10−/− mouse model of colitis." (PMID 21060867, 2010). "Interestingly, GFP-tagged T cells derived from mice with a Foxp3 allele that directs expression of a nonfunctional fusion protein of Foxp3-GFP failed to induce colitis upon transfer into lymphopenic recipients." (PMID 19272184, 2009). "Furthermore, transfer of naive T cells to Il23a−/−Rag1−/− mice fails to elicit colitis and is associated with an increase in the frequency of CD4+Foxp3+ cells in the intestine." (PMID 18400195, 2008). "Finally, the expansion of Foxp3+IFN-γ+ Tregs following STAT6 inhibition during acute colitis may reflect an adaptive regulatory phenotype rather than pathogenic plasticity." (PMID 41203944, 2025). "Furthermore, C57BL/6 mice monocolonized with Pd have markedly increased FoxP3+ Treg cells in their colonic mucosa, and oral treatment with Pd lysate antigens significantly increase CD4+CD25+FoxP3+ cells in mesenteric lymph nodes of mice with dextran sodium sulfate (DSS)-induced colitis." (PMID 39737164, 2024). "Indeed, NOD2−/− recipients of lamina propria mononuclear cells (LPMC) from ethanol-treated NOD2−/− donors that had been depleted of CD4+LAP+Foxp3− cells exhibited increased TNBS-induced weight loss when compared to NOD2−/− recipients of intact LPMCs, which did not develop colitis." (PMID 36012618, 2022). "However, one study showed that only injection of OVA-specific Tr1 cells, and not FOXP3+ Tregs, multiple weeks after colitis onset resolved intestinal inflammation which indicates that mainly Tr1 cells are able to expand in vivo to control inflammation and ongoing disease and ongoing disease." (PMID 36389662, 2022). "In addition, the percentages of CD3e+CD4+CD25+Foxp3+ cells in the spleens of mice with DSS-induced colitis that were treated with M2c macrophage exosomes were significantly increased (13.5 ± 3%; P < 0.001) compared with PBS-treated mice with DSS-induced colitis (9.3 ± 1%)." (PMID 31749791, 2019). "In addition, other types of colitis, such as infectious colitis and ischemic colitis, were not included in this study to exclude the impact of other inflammation on the colonic expression of FOXP3." (PMID 30918515, 2019). "We observed increased IL-10 mRNA levels, concurrent with increased expression of forkhead box P3 (Foxp3) mRNA, the master regulatory gene for regulatory T cells, in splenic tissues from DSS-induced colitis mice administered with DCF0620 (data not shown)." (PMID 41567191, 2025). "We found significantly increased IL-17A+ CD4+ T cells, after DDC+DSS treatment while frequencies of Foxp3+ Treg, and IFNγ+ CD4+ T cells were comparable between DDC treated mice with and without acute DSS colitis." (PMID 38510236, 2024). "Although there was no significant change in the proportional abundance of the Foxp3+ CD4+ TREG cluster between control and CPI colitis, there were a few qualitative changes in the transcriptome." (PMID 37872166, 2023).
colitis (continued). "Even in inflammatory settings such as in the T cell-transfer induced experimental colitis model, dominant TCRα clonotypes were shared between IFN-γ- and IL-17-producing but not Foxp3+ Treg cells." (PMID 36310871, 2022). "Intriguingly, the number of CD4+CD25 + cells was increased in the spleen and MLN of DSS-treated mice, while the percentage of CD4+FOXP3+ cells was decreased, suggested the absence of Treg cells in DSS-induced colitis." (PMID 33967779, 2021). "In this study, we provide evidence demonstrating that combined delivery of IL-2 immunocomplexes and anti-IL-5 mAb is highly effective at expanding Foxp3+ Treg cells in the absence of eosinophilia and ameliorating DSS-induced colitis in mice." (PMID 30930900, 2019). "Collectively, these data suggested that DSS-induced colitis was not aggravated in CCR7KO mice in comparison with WT mice, despite the immobilization of Foxp3+ Tregs." (PMID 26908454, 2016). "Unlike observations in the acute colitis model described earlier, comparison of staining with anti-CD3 and anti-Foxp3 antibody revealed an increased Foxp3:CD3 ratio in the colon of CD200tg mice compared with the other three groups." (PMID 26841120, 2016). "In the DSS colitis model, administration of EPM but not F. prausnitzii increased the number of Foxp3+ T cells in the MLNs." (PMID 25910186, 2015). "Ameliorated colitis through AhR signaling activation, increased the expression of anti-inflammatory cytokines, and resulted in the expansion of IL-10-producing CD4+ T cells and IL-22-producing CD3−RORγt+ cells, but not CD4+Foxp3+ regulatory T cells." (PMID 40756994, 2025). "This hypothesis is supported by our finding that the protective effect of liver cholestasis on colitis severity was not detectable in the CD4+CD45RBhigh T-cell transfer colitis model, 45 in which Foxp3+ Treg cells are largely absent." (PMID 38839272, 2024). "Myeloid knockout of HIF-1α ameliorated murine dextran sodium sulfate (DSS)-induced colitis while myeloid HIF-2α knockout aggravated colitis by increasing myeloperoxidase (MPO)+ and CD3+FoxP3+ T regulatory cell recruitment deep in the colon with no apparent differences in F4/80+ cell infiltration." (PMID 37124241, 2023). "The results showed that percentages of CD4+CXCR5+PD-1+ Tfh and Tfh/Tfr ratios in the MLNs and spleen of colitis mice increased significantly compared to those of normal mice (p < 0.05), while no statistical difference was found in CD4+CXCR5+Foxp3+ Tfr (p > 0.05)." (PMID 34707499, 2021). "FOXP3+ CD4+ T cells were increased in numbers but not frequencies, while RORγt+ (also known as RORC+) CD4+ T cells were increased in frequencies and numbers, in colitic mice exposed to PFOS while undergoing colitis." (PMID 34792120, 2021). "In this model, immunodeficient mice lacking mature T and B cells (e.g., Rag1 -/-) develop colitis a few weeks following the transfer of naïve CD4+ T cells (CD25negCD45RBhigh) unless a fraction containing Treg cells (e.g., CD45RBlow or CD4+CD25+FOXP3+) are co-injected." (PMID 34421921, 2021). "Our previous studies showed that a novel forkhead box protein P3 (Foxp3) negative Tregs (Treg-of-B cells), induced by culturing naïve CD4+ T cells with B cells, could protect against colitis and downregulate T helper (Th) 1 and Th17 cell cytokines in T cell-mediated colitis." (PMID 39085655, 2024).
melanoma (281 papers, 2007 to 2025). A malignant, usually aggressive tumor composed of atypical, neoplastic melanocytes. "As a novel finding, we demonstrate a prognostic impact of FOXP3 TIL count in a large patient series of melanoma lymph node metastases, with low FOXP3 TIL counts being associated with reduced survival." (PMID 39883679, 2025). "In contrast, cancer-FoxP3 has been identified as a biomarker associated with poor prognosis in pancreatic cancer, lung cancer, thyroid cancer, and melanoma." (PMID 39150932, 2024). "We also reveal evidence for CEACAM1 expression on CD4+ T cells that are phenotypically consistent with FoxP3+ regulatory T cells whose presence correlates with the melanoma-associated TME using multiple approaches." (PMID 38956268, 2024). "CD39 is mainly a (FOXP3 +) Treg marker; in fact in melanoma and colon cancer models, ENTPD1-deficient mice displayed impaired Treg-suppressive functions." (PMID 37142825, 2024). "Neoadjuvant treatment with anti-CTLA4 of advanced melanoma was associated with increased levels of circulating FOXP3-positive Treg cells, which interestingly correlated with a better prognosis." (PMID 37568571, 2023). "High levels of Foxp3-positive lymphocytes have been linked to worse prognosis, e.g., colorectal cancer, melanomas, and lung carcinomas." (PMID 35326661, 2022). "High levels of FoxP3 lymphocytes are linked to worse cancer prognosis, e.g., colorectal, melanomas and lung carcinomas." (PMID 36289746, 2022). "We also found that GrB+ lymphocytes associate positively with both IDO+ melanoma cells and tumor nest macrophages and moderately with FoxP3 Tregs and IDO+ stromal immune cells." (PMID 36551965, 2022). "It has been reported in this regard that a higher Foxp3+ CD4+ regulatory T cell level at baseline is significantly associated with favorable outcomes with ipilimumab therapy in patients with melanoma." (PMID 36237314, 2022). "To test these associations in different tumor types, we selected three T/NK cell modules (FLT3LG.mod, PDCD1.mod and FOXP3.mod that were associated with patient survival (in melanoma, head and neck and bladder tumors, respectively)." (PMID 26398410, 2015). "Accumulation of FOXP3+ regulatory T cells in SLNs was demonstrated to be associated with poor prognosis in breast and gastric cancer as well as in melanoma." (PMID 23418928, 2013). "In the present study, FoxP3+ cells were strongly associated with other effector T cells, and similar results have been reported in melanoma." (PMID 19641607, 2009). "The accumulation of FoxP3+ Tregs, especially a relatively high ratio of Tregs: T effector cells (Teffs), is often associated with a poor prognosis in many tumors, including ovarian cancer, lung cancer, glioblastoma, melanoma and other malignancies." (PMID 39534095, 2024). "Notably, mice with Opn-deficient Foxp3+ Tregs exhibited enhanced anti-tumor immunity and reduced tumor burden when challenged with B16 melanoma cells." (PMID 39272810, 2024). "It is known that melanoma is one of the main targets for immunotherapy with checkpoint inhibitors due to its high mutation load, which contributes to its high immunogenicity, thus the study was carried out on C57Bl/6 FoxP3-EGFP mice with B16F0 melanoma." (PMID 38435479, 2023). "On the other hand, while the higher count of FoxP3-positive tumor cells predicts better survival in gastric and prostate cancers, in melanoma and NSCLC, high expression was associated with an unfavorable clinical prognosis, leading to shorter overall survival and recurrence-free survival." (PMID 36980787, 2023). "In the field of tumor immunotherapy, researchers have designed some ASOs that silenced immune suppresser gene expression, such as cytotoxic T-lymphocyte associated protein 4 (CTLA-4) and forkhead box P3 (Foxp3), and delayed tumor growth in murine melanoma models." (PMID 37175900, 2023).
melanoma (continued). "In line, therapeutic application of the agonist anti-GITR monoclonal antibody DTA-1 in B16F10 melanoma-bearing mice induced regression of tumors accompanied by decreased accumulation of intra-tumor Treg cells due both to loss of Foxp3 expression and impaired infiltration." (PMID 34539668, 2021). "Indeed, we showed that higher expression of CD300A was associated with lower expression of Foxp3 and longer survival times of melanoma patients." (PMID 34751648, 2021). "The results under the association of FOXP3+ TILs with prognosis in melanoma are conflicting." (PMID 33916279, 2021). "The expression of FOXP3 in tumor cells is considered a mechanism of escaping immune destruction of malignant cells, being associated with tumorigenesis and tumor progression, being proposed as an independent prognosis marker in melanoma." (PMID 33274240, 2020). "Notably, another study including 5 ACT trials found that levels of peripheral CD4 + Foxp3+ Tregs were negatively associated with clinical response to adoptive immunotherapy in melanoma patients." (PMID 29750176, 2018). "Collectively, the proposed method successfully captured an important feature of melanoma without relying on the existing criteria of FOXP3+ T cells, revealing a hidden association between the T cell profile and melanoma, and providing new insights into FOXP3+ T cells and Tregs." (PMID 26864030, 2016). "Indeed, further in silico gene expression analysis has revealed a significant association between Wnt5a and Foxp3 gene expression levels in human melanomas." (PMID 25339948, 2014). "Increased Foxp3 expression in T cells, peripheral blood and tumors has been associated with disease progression and a worse prognosis in cancer patients, including melanoma patients." (PMID 24179494, 2013). "FOXp3-positive, IL-10 producing T lymphocytes were recently reported in tumour, blood and ascites from patients with advanced melanoma, and were associated with melanoma-related immunosuppression." (PMID 17565341, 2007). "Tumor-infiltrating lymphocytes produced more IFN-gamma and MART-1 CD8+ T-cells, along with inducing a decrease in FoxP3+ T-cells, in the injected melanoma lesions post-injection when compared to the untreated melanoma control." (PMID 40004731, 2025). "TGF-β levels have been correlated with T cell dysfunction in melanoma and have also been shown to increase expression of forkhead box P3 (FOXP3), which controls regulatory T cell (Treg) development." (PMID 40872475, 2025). "In line with our in vitro results, IHC analysis performed on melanoma patient samples revealed higher expression of FoxP3 in male samples with respect to female." (PMID 39888245, 2025). "In a B16F10 melanoma model, auranofin treatment increased lung tumor coverage, IL-10 serum levels, and FOXP3+CD44+CD4+ T cell frequencies." (PMID 41300507, 2025). "Several studies have examined correlations between melanoma prognostic factors—such as Breslow thickness and mitotic index—and the expression of FOXP3+ regulatory T cells and dendritic cells within the tumor stroma." (PMID 39976551, 2025). "In solid tumors such as lung, melanoma, and esophageal cancer, high infiltration of FoxP3+ Tregs in tumor tissues was detected, and an increased immune response was observed after selective depletion of FoxP3+ Tregs using different immunotherapies." (PMID 40216744, 2025). "Human DC2/moDC and TAM signatures were generated based on our scRNAseq and correlated with three Treg-associated genes (i.e., FOXP3, CTLA4, and TIGIT) in patients undergoing RT of radioresistant tumors (i.e., melanoma, glioblastoma, and head and neck cancer)." (PMID 40146036, 2025). "Within resistance to immunotherapy in melanoma, levels of regulatory T-cells expressing forkhead box P3 (FOXP3) are elevated." (PMID 38672652, 2024).